E2F1 (E2F transcription factor 1)
Diseases named in the same sentence as E2F1 in open-access papers (continued):
Sharing a sentence is not in itself a finding about the gene and the disease.
ovarian carcinoma (continued). "We found that silencing E2F1 triggered senescence in ovarian carcinoma cells, supporting the premise that E2F1 targets miR-519d directly, decreasing its expression." (PMID 28146423, 2017). "The findings suggest that E2F1 has potent oncogenic effects in ovarian carcinoma of different type and origin." (PMID 28146423, 2017). "E2F1 expression is increased in ovarian carcinoma tissues, and it is believed that E2F1 is a promoter of the development of ovarian carcinoma." (PMID 28146423, 2017). "RNF126 was found to positively regulate BRCA1 by directly interacting with E2F1 for homologous recombination in breast and ovarian cancer." (PMID 29052520, 2017). "We found that miR-519d transfection decreased MMP2, MMP9, STAT3, and HuR expression in ovarian carcinoma cells; at the same time, E2F1 increased the expression of these genes." (PMID 28146423, 2017). "We found that E2F1 promoted ovarian carcinoma cell proliferation, G1–S progression, survival, migration, and invasion in vitro and promoted ovarian carcinoma tumorigenesis and tumor growth in vivo." (PMID 28146423, 2017). "The E2F1/miR-519d/RhoC signaling pathway is of significant importance and shows promise as a target for diagnosing and treating ovarian carcinoma." (PMID 28146423, 2017). "We also compared E2F1 expression levels in 96 cases of type II tumors and 23 fallopian tube tissues, and E2F1 expression was also significantly elevated in the ovarian carcinoma tissues." (PMID 28146423, 2017). "E2F1 was overexpressed in type I and type II ovarian carcinoma as compared to normal ovary tissues and normal fallopian tube tissues, respectively." (PMID 28146423, 2017). "Our findings suggest that E2F1 functions as an oncogene in ovarian carcinoma in part by upregulating Bcl-2, cyclin D1, survivin, MMP2, and MMP9 expression." (PMID 28146423, 2017). "After E2F1 plasmid transfection and E2F1-microRNA-519d (miR-519d)/si-RhoC (Ras homolog gene family member C) co-transfection, ovarian cancer cell phenotypes and the related molecules were examined in vitro and in vivo." (PMID 28146423, 2017). "We provide evidence that E2F1/miR-519d/RhoC is a promising signaling pathway for diagnosing and treating ovarian carcinoma." (PMID 28146423, 2017). "Some of them, including E2F1 and several members of the Sp-family of transcription factors, have been identified as biomarkers of ovarian cancer." (PMID 25110883, 2014). "Here, we report that E2F1 was downregulated at the mRNA and protein levels in the three ovarian cancer cell lines examined by treatment with diclofenac and indomethacin." (PMID 23637916, 2013). "We report that NSAIDs significantly reduced ovarian cancer cell growth in vitro and in vivo, and, using microarray analysis, we identified the transcription factor E2F1 as a mediator of this effect." (PMID 23637916, 2013). "Topological analysis of the network reveals a set of 15 target genes that are regulated by SP3 or NFκB1 in normal cells, but by E2F1 in ovarian cancer." (PMID 22548828, 2012). "E2F1 was knocked down in ovarian cancer cells, and CCK-8 assays were then performed." (PMID 38424195, 2024). "Thus, we knocked down these m5C readers separately in ovarian cancer cells and evaluated the changes in E2F1 expression." (PMID 38424195, 2024). "The study indicates that focusing on NSUN2 and E2F1 could be a potential treatment approach for ovarian cancer." (PMID 38424195, 2024). "We propose that the increased proliferation capability observed in drug-sensitive ovarian cancer cells when co-cultured with drug-resistant cells may be attributed to the overexpression and activity of E2F1." (PMID 38344207, 2024). "Furthermore, we analyzed the correlation between the expression of NSUN2 and E2F1 in ovarian cancer." (PMID 38424195, 2024). "Additionally, survival analysis revealed that ovarian cancer patients with higher E2F1 expression tended to have shorter overall survival and progression-free survival times." (PMID 38424195, 2024).
ovarian carcinoma (continued). "Taken together, these data indicate the crucial function of E2F1 in ovarian cancer progression." (PMID 38424195, 2024). "STMN1 promotes the proliferation and migration of ovarian cancer and is regulated by E2F1." (PMID 35186166, 2022). "Furthermore, we found a strong correlation between E2F1 and RNaseH2A expression and an inverse correlation between RNaseH2A expression and poor prognosis in patients with colorectal, cervical, or ovarian cancer via TCGA database analysis." (PMID 36577784, 2022). "Transcriptional activation of DDX23 by E2F1 in turn up-regulates DDX23 in ovarian cancer." (PMID 34966670, 2021). "Our results imply that EIF5A2 positively regulates stemness in ovarian cancer cells via E2F1/KLF4 pathway and may serve as a potential target in CSCs-targeted therapy for ovarian cancer." (PMID 33726845, 2021). "E2F1 was found to induce pro-proliferation genes or pro-apoptosis genes in response to high and low levels, respectively, thereby either stimulating cancer growth or improving the overall prognosis of ovarian cancer." (PMID 35052372, 2021). "Furthermore, we confirmed that DDX23 was transcriptionally activated by the transcription factor (TF) E2F1 in ovarian cancer using luciferase reporter assays and chromatin immunoprecipitation (ChIP) assays." (PMID 34966670, 2021). "The concentrations of p16, p21, and E2F1 increase in ovarian cancer." (PMID 33080800, 2020). "Given that ZC3H18 depletion caused BRCA1 promoter methylation and E2F1 recruitment to the BRCA1 promoter, we reasoned that E2F1 might repress BRCA1 expression in ovarian cancer cells by recruiting DNMT1 when ZC3H18 was depleted." (PMID 31604914, 2019). "In the E2F family of transcription factors, E2F2, E2F3, E2F4, and E2F8 expression is increased and may play oncogenic roles in ovarian carcinoma, and exert the same effects as E2F1." (PMID 28146423, 2017). "E2F1 expression levels in ovarian carcinoma tissue were examined by immunohistochemistry." (PMID 28146423, 2017). "Taken together, we hypothesize that E2F4 could have the same oncogenic effects as E2F1 on ovarian carcinoma by suppressing miR-519d." (PMID 28146423, 2017). "We found that E2F1 plasmid and RhoC siRNA co-transfection greatly reversed the oncogenic role of E2F1 in ovarian carcinoma cell phenotype, revealing that RhoC plays a central role in the oncogenic regulation of E2F1/miR-519d on ovarian carcinogenesis and development." (PMID 28146423, 2017). "We report the molecular mechanism of E2F1 in ovarian carcinoma tumorigenesis and progression." (PMID 28146423, 2017). "In conclusion, NSAIDs diclofenac and indomethacin exert an anti-proliferative effect in ovarian cancer in vitro and in vivo and the effects of NSAIDs may be mediated, in part, by downregulation of E2F1." (PMID 23637916, 2013). "Since the expression of both E2F1 and its target genes is downregulated upon treatment with diclofenac and indomethacin, we wanted to determine whether E2F1 was involved in the growth inhibitory effects of NSAIDs in ovarian cancer cells." (PMID 23637916, 2013). "In ovarian cancer, up-regulation of E2F1 contributes to uncontrolled cell proliferation." (PMID 22548828, 2012). "Thus, we predict that E2F1 negatively regulates HSD17B2 in ovarian cancer and that reduced HSD17B2 results in an excess of estradiol, which in turn activates cell-proliferation genes through the activation of ESR1." (PMID 22548828, 2012). "Furthermore, our analysis of the ovarian cancer data indicates that E2F1, and direct downstream targets of the WNT pathway (survivin, ID2 and vimentin) critical in cell-cycle progression, are up-regulated." (PMID 22548828, 2012). "We see that E2F1 expression is elevated in ovarian cancer, while HSD17B2 expression is reduced." (PMID 22548828, 2012).
ovarian carcinoma (continued). "Its role in ovarian cancer has been unclear, as other research groups have found similar favourable survival with increased E2F1 pathway activation, while other findings have shown favourable survival with decreased E2F1 gene expression by RT-PCR." (PMID 21799864, 2011). "Indeed, in ovarian cancer, the proliferation-promoting E2F1 and E2F2 transcription factors were overexpressed, compared with healthy control tissues." (PMID 20226085, 2010). "Similarly, studies with histopathology grade 2 ovarian cancers demonstrated that transcription factors E2F-1 and E2F-2 play a critical role in promoting tumor metastasis." (PMID 20196847, 2010). "NSUN2 is aberrantly upregulated in ovarian cancer and promotes the malignancy of ovarian cancer through regulating the expression of the oncogenic driver E2F transcription factor 1 (E2F1) in an m5C-dependent manner, and E2F1 facilitates the transcription of NSUN2 as well as MYBL2 and RAD54L." (PMID 38424195, 2024). "E2F1 gene rs3213173 and rs3213176 polymorphisms confer no risk of ovarian cancer." (PMID 35833075, 2022). "E2F1 gene rs3213173 and rs3213176 polymorphisms confer no risk to ovarian cancer risk." (PMID 35833075, 2022). "Moreover, DDX23 was transcriptionally activated by the E2F1 in ovarian cancer." (PMID 34966670, 2021). "Consequently, RAD51-AS1, a target gene of E2F1, may be involved in the regulation of cell cycle or apoptosis and participate in ovarian cancer development." (PMID 28667302, 2017). "We co-transfected ovarian carcinoma cells with E2F1 plasmid and miR-519d mimic, and found that miR-519d greatly reversed the effect of E2F1, revealing that miR-519d plays a central role in the oncogenic effects of E2F1 on ovarian carcinogenesis and development." (PMID 28146423, 2017). "Additionally, we observed an inhibitory effect of Lan1 and Lan2 on the expression of the transcription factor E2F1, suggesting that the anti-proliferative effect of this antagonist in ovarian cancer may be mediated, in part, by the down-regulation of E2F1." (PMID 28861689, 2017). "Topological analysis of the complete network also suggests cross-regulation of angiogenesis-specific genes through SP3, NFκB1 and E2F1 in the normal and ovarian cancer networks, and we hypothesize that deregulation of these angiogenic genes may be associated with oncogenesis." (PMID 22548828, 2012). "To determine the regulatory effect of NSUN2 on E2F1, we measured E2F1 protein expression upon NSUN2 knockdown in ovarian cancer cells." (PMID 38424195, 2024). "We also performed polysome profiling assays in ovarian cancer cells to examine the distribution of the YBX1 protein and E2F1 mRNA in the translationally active and translationally inactive fractions." (PMID 38424195, 2024). "We also assessed the effect of NSUN2 on E2F1 mRNA stability and found that NSUN2 depletion reduced the half-life of E2F1 mRNA in ovarian cancer cells, suggesting that NSUN2 promoted m5C modification of E2F1 mRNA and facilitated its stability." (PMID 38424195, 2024). "E2F1 can promote the proliferation and migration of ovarian cancer cells by regulating stathmin 1 (STMN1) overexpression, and high STMN1 expression in ovarian cancer often indicates a poor prognosis." (PMID 38992083, 2024). "Considering that YBX1 and NSUN2 regulate E2F1 expression in ovarian cancer, we examined the role of YBX1 in ovarian cancer." (PMID 38424195, 2024). "We integrated the E2F1 ChIP-seq and RNA-seq data for NSUN2 in ovarian cancer cells and found that 120 genes were potential targets of both NSUN2 and E2F1." (PMID 38424195, 2024). "Accumulated studies have demonstrated that E2F1 can mediate the EMT process in various cancers, including non-small cell lung carcinoma, ovarian cancer, clear cell renal cell carcinoma, and BC." (PMID 37160894, 2023). "Our study also revealed that DDX23 was transcriptionally activated by E2F1, contributing to the elevated expression of DDX23 in ovarian cancer." (PMID 34966670, 2021).
ovarian carcinoma (continued). "Co-expression analysis revealed that the mRNA expression of E2F1 and DDX23 were positively correlated in ovarian cancer (Spearman’s correlation = 0.38, P = 1.34e-7)." (PMID 34966670, 2021). "Previous data suggested that the proliferation-promoting E2F1 and, especially, E2F2 played pivotal roles in the tumor biology of ovarian cancer." (PMID 26967247, 2016). "It has been reported that RU486 induces G1-S blockage of the cell cycle in human ovarian cancer cells and that RU486 reduces the activity of cdk2, enzyme that is involved in the regulation of the transcription factor E2F1 which modulates S-phase progression." (PMID 24982875, 2014). "Importantly we found that ectopic E2F1 expression reversed the growth-inhibitory effects of NSAIDs suggesting that NSAIDs could act in part through a mechanism involving E2F1 downregulation in ovarian cancer cells." (PMID 23637916, 2013). "Our GRNI analysis suggests that E2F1 interacts with DKK-1 in the normal ovary, but that this interaction is lost in ovarian cancer." (PMID 22548828, 2012). "E2F-1 has been shown to have growth promoting activity in EOC and is over expressed in roughly half of the ovarian cancers." (PMID 20196847, 2010). "Moreover, E2F1 transcriptionally regulates the expression of the oncogenes MYBL2 and RAD54L, driving ovarian cancer progression." (PMID 38424195, 2024). "E2F1 upregulates NSUN2 expression by activating its transcription, suggesting that genetic regulation and transcriptional regulation synergistically contribute to NSUN2 upregulation in ovarian cancer." (PMID 38424195, 2024). "To determine whether E2F1 was involved in the regulation of DDX23 transcription, we first detected the expression of DDX23 in E2F1 knockdown and control ovarian cancer cells." (PMID 34966670, 2021). "We subsequently confirmed that E2F1 could bind to the DDX23 promoter region directly and regulate DDX23 transcription in ovarian cancer cells." (PMID 34966670, 2021). "To determine whether the induction of autophagy following E2F1/4 inhibition was DIRAS3 dependent, we treated A2780 and SKOv3 ovarian cancer cells with DIRAS3 or control siRNA." (PMID 31052266, 2019). "Downregulation of E2F1/4 correlated with the induction of autophagy and upregulation of DIRAS3 protein determined by immunofluorescence staining of LC3 puncta and DIRAS3 protein in A2780, SKOv3, and ES2 ovarian cancer cells." (PMID 31052266, 2019). "In conclusion, our study identifies a novel molecular mechanism for E2F1, whereby it targets miR-519d to upregulate RhoC, Bcl-2, cyclin D1, survivin, MMP2, MMP9, STAT3 and HuR expression, promoting tumorigenesis and progression in ovarian carcinoma." (PMID 28146423, 2017). "In addition, although the overactivity of E2F1 increased cell death in cancer cells, the expression of E2F1 is increased and was correlated with FIGO stage, tumor grade in ovarian cancer." (PMID 27385216, 2016). "Furthermore, we demonstrated that STMN1 was regulated by E2F1, which might be an important mechanism through which STMN1 promotes proliferation in ovarian cancer cells." (PMID 35186166, 2022). "To further confirm that NSUN2-mediated m5C modification regulates E2F1 expression in a manner dependent on YBX1, we overexpressed NSUN2 in ovarian cancer cells with or without YBX1 expression and assessed the expression of E2F1." (PMID 38424195, 2024). "Neither angiogenesis nor the transcription factors E2F1, SP3 and NFκB1 were identified in the original analysis of the ovarian cancer data." (PMID 22548828, 2012).
bladder cancer (64 papers, 2008 to 2025). "In bladder cancer, the transcription factor E2F1 directly activates RAD54L, regulating DDR, and is linked to poor prognosis." (PMID 35559013, 2022). "Among different cancer types, E2F1 overexpression has been linked to tumor progression in prostate and bladder cancers, which indicates a tumor promoting role of E2F1 in these cancer types." (PMID 25816777, 2015). "In the case of bladder cancer, an E2F1 gene expression signature has been associated with muscle invasive bladder cancer and been shown to predict progression of superficial bladder cancers to the more aggressive muscle invasive bladder cancers." (PMID 25816777, 2015). "In a word, SLC16A1-AS1 in bladder cancer is implicated in several key aspects of cancer progression, particularly through its role in metabolic reprogramming, invasion, and proliferation, mediated by its interaction with E2F1 and MCT1." (PMID 38555465, 2024). "Therefore, in this study, DNA repair genes related to E2F1 associated with bladder cancer progression were investigated." (PMID 33261027, 2020). "Therefore, we sought to determine the association of bladder cancer recurrence with the expression of E2F1 and RAD54L." (PMID 33261027, 2020). "Thus, we examined the activation of the MAPK pathway and E2F1 to further uncover the underlying mechanisms of hnRNP-L in bladder cancer." (PMID 28088793, 2017). "The interaction between SLC16A1-AS1 and E2F1 in bladder cancer leads to changes in the metabolic pathways of the cancer cells, a process termed metabolic reprogramming." (PMID 38555465, 2024). "The transcription factor E2F1 has been identified as an oncogenic element in colorectal and bladder cancer." (PMID 38012557, 2023). "Further studies have confirmed that TMPO-AS1 induces growth of bladder cancer through an E2F1-dependent manner." (PMID 36467407, 2022). "lncRNA-SLC16A1-AS1 has been shown to induce bladder cancer metabolic reprogramming as target and coactivator of E2F1." (PMID 39280890, 2022). "Inoculation of stably transfected RT4 bladder cancer cells into nude mice has also verified that TMPO-AS1 can enhance bladder cancer growth through E2F1 in vivo." (PMID 36467407, 2022). "Firstly, lncRNA SLC16A1-AS1 has been identified to play a vital role in the metabolic reprogramming as targeting and co-activating of E2F1 in patients with bladder cancer." (PMID 36212122, 2022). "This study has verified the importance of a TMPO-AS1/E2F1 positive regulatory circuit in the development of bladder cancer." (PMID 36467407, 2022). "In this study, we demonstrated that in conjunction with PCGs, E2F1 induces expression of lncRNAs in bladder cancer, which are relevant for disease progression." (PMID 32863950, 2020). "This study also confirmed that DNA breaks are repaired by RAD54L induced by E2F1 in bladder cancer cells treated with MMC." (PMID 33261027, 2020). "In particular, E2F1 abundance is the key event in superficial-to-invasive bladder cancer (BC) progression." (PMID 32863950, 2020). "In summary, our work shows that FOXD2-AS1 exhibit strong effects on bladder cancer progression and recurrence thruogh a positive feedback loop with Akt and E2F1." (PMID 29445134, 2018). "The positive correlation between FOXD2-AS1 and E2F1 was also obeserved in 84 cases of bladder cancer tissues using qRT-PCR." (PMID 29445134, 2018). "As the results showed, the half-time of E2F1 was prolonged in FOXD2-AS1 expression plasmid treated bladder cancer cells than in corresponding empty vectors treated cells." (PMID 29445134, 2018). "A total of nine chr3p25 and chr11p11 genes were functionally connected to genes in the KEGG bladder cancer pathway (E2F1, E2F3, EGFR, RAF1, RB1) or to other cancer-related genes (AKT2, PIK3CA, RB1, TRIO)." (PMID 29140994, 2017). "Few reports were in contrast with our findings; low E2F-1 was associated with shortened survival of DLBCL and bladder carcinoma patients." (PMID 26601052, 2015).